LIMK2 (LIM domain kinase 2)
Diseases named in the same sentence as LIMK2 in open-access papers (continued):
Sharing a sentence is not in itself a finding about the gene and the disease.
colon cancer (3 papers, 2017 to 2021). "The actin depolymerization pathway has been recognized as a critical cellular response that controls the apoptosis and inhibition of cell migration triggered in prostate, breast and colon cancer cells through ROCK1/LIMK2/Cofilin cascades." (PMID 27709782, 2017). "FuSiOn identified ten kinases (BMP2K, DCLK3, LIMK2, MAP2K5/MEK5, MAP3K3/MEKK3, ROS1, SIK2, TAOK2, ULK1, and ULK2) whose depletion mimicked the phenotypic effect of p62 depletion in HCT116 colon cancer cells." (PMID 33101709, 2020).
glioma (3 papers, 2010 to 2014). A benign or malignant brain and spinal cord tumor that arises from glial cells (astrocytes, oligodendrocytes, ependymal cells). "In summary, LIMK1 and LIMK2 down-regulation correlates with better overall survival in glioma patients; and DNA copy number gains of LIMK1 correlate with worse survival in GBM patients." (PMID 25237832, 2014). "Some of these, such as DYRK3, play a role in cell growth and development in the glioma cell line, whereas LIMK2 is involved in stress fiber and focal adhesion formation and membrane blebs during the apoptotic process." (PMID 21637621, 2010). "Based on gene expression, glioma patients (grades II–IV) with downregulated LIMK1 and LIMK2 had significantly better overall survival (p>0.05)." (PMID 25237832, 2014).
erectile dysfunction (2 papers, 2019 to 2021). Persistent or recurrent inability to achieve or to maintain an erection during sexual activity. "Furthermore, chronic inhibition of the LIMK2–cofilin pathway significantly restrained the cavernosal veno-occlusive dysfunction, the primary pathophysiologic mechanism of post-prostatectomy erectile dysfunction through suppressing fibrosis in the corpus cavernosum." (PMID 35011645, 2021). "Recent evidence demonstrated that chronic inhibition of LIMK2 prevented cavernosal fibrosis and cavernosal veno-occlusive dysfunction (CVOD), the primary mechanism of post-prostatectomy erectile dysfunction." (PMID 35011645, 2021).
glioblastoma (2 papers, 2014 to 2023). The most malignant astrocytic tumor (WHO grade IV). "An interaction between endogenous PKCζ and LIMK1, but not LIMK2, was shown in the LN229 glioblastoma cell line upon EGF stimulation." (PMID 36899941, 2023). "The glioblastoma U87 and the schwannoma ST88-14 cell lines were chosen because their NF1 levels are low, meaning that in those cell lines LIMK2 activity is not downregulated by NF1." (PMID 25593987, 2014).
liver cancer (2 papers, 2021 to 2022). An epithelial or non-epithelial malignant neoplasm that arises from the liver. "With the aim of evaluating the prognostic effects of LIMK1 and LIMK2, we performed a Kaplan-Meier survival analysis on liver cancer (HCC) RNA-seq data, collected from 364 patients." (PMID 34843456, 2021). "Comparing normal liver tissue samples (225 patients) and liver hepatocellular carcinoma (LIHC) samples (371 patients), the expression of the genes: RhoA, Rac1, LIMK1, LIMK2, ROCK1, ROCK2, MLCK2, and PAK4 is upregulated in liver cancer." (PMID 35241781, 2022).
Lung Squamous Cell Carcinoma (2 papers, 2022 to 2023). "As previously reported, LIMK2 was a serine/threonine protein kinase that positively associated with OS in lung squamous cell carcinoma (LUSC), which was consistent with our findings." (PMID 37189142, 2023). "Our researchers found that LIMK2 was highly expressed in many cancers, such as liver cancer and lung squamous cell carcinoma." (PMID 35273591, 2022).
melanoma (2 papers, 2016 to 2020). A malignant, usually aggressive tumor composed of atypical, neoplastic melanocytes. "Interestingly, the gene LIMK2 has been previously associated with melanoma susceptibility in Duroc pigs." (PMID 32695139, 2020). "As shown in, LIMK2 and p-cofilin were readily apparent in lungs from WT mice without metastatic disease and the detection of both was decreased by melanoma metastasis." (PMID 27198666, 2016).
Parkinson’s (2 papers, 2020 to 2024). "LIMK2 is also involved in neurodevelopmental disorders and neurodegenerative diseases, including AD, Parkinson’s, and schizophrenia." (PMID 39596356, 2024).
schizophrenia (2 papers, 2023 to 2024). A major psychotic disorder characterized by abnormalities in the perception or expression of reality. "Of particular interest, LIMK2 were consistently upregulated in ASD (p = 0.0003), schizophrenia (p = 3.18 × 10−9), and bipolar disorder (p = 0.0003)." (PMID 36253440, 2023).
status epilepticus (2 papers, 2015 to 2016). Status epilepticus is defined as a continuous seizure lasting more than 30 min, or two or more seizures without full recovery of consciousness between any of them. "Recently, we have reported that up-regulation of LIM kinase 2 (LIMK2) expression induces HMGB1 export from neuronal nuclei during status epilepticus (SE)-induced programmed neuronal necrosis in the rat hippocampus." (PMID 27147971, 2016). "Recently, we have reported that LIM kinase 2 (LIMK2) involves programmed necrotic neuronal deaths induced by aberrant cyclin D1 expression following status epilepticus (SE)." (PMID 26438559, 2015).
age (1 paper, 2019). A temporal measurement of the time period elapsed since an identifiable point in the life cycle of an organism. "Similarly, a recent study using aged rats showed that the RhoA/ROCK1/LIMK2/Cofilin pathway was involved in cavernosal fibrosis and ED caused by advanced age, suggesting that these factors might be novel targets in the treatment of age-related cavernosal fibrosis." (PMID 30870492, 2019).
Alzheimer disease (1 paper, 2024). A progressive, neurodegenerative disease characterized by loss of function and death of nerve cells in several areas of the brain leading to loss of cognitive function such as memory and language. "In addition, ENST00000340552 (LIMK2) was strongly associated with Alzheimer’s disease age of onset (ADAOO), accelerating AD onset by approximately 12.6 years." (PMID 39596356, 2024).
Azoospermia (1 paper, 2022). Absence of any measurable level of sperm,whereby spermatozoa cannot be observed even after centrifugation of the semen pellet. "Interestingly, LIMK2 ranks high in the comprehensive list of 654 human infertility-related genes that have been sequenced in the study of nonobstructive azoospermia, the most common form of azoospermia, performed by Li and collaborators." (PMID 35159213, 2022).
benign prostatic hyperplasia (1 paper, 2007). A non-cancerous nodular enlargement of the prostate gland. "We have noted that LIMK1 but not LIMK2 is overexpressed in highly aggressive and metastatic PC3 prostate cancer cells and in prostate tumor tissues compared to benign prostatic hyperplasia (BPH-1) cells and normal prostatic epithelium." (PMID 17559677, 2007).
cervical cancer (1 paper, 2024). A primary or metastatic malignant neoplasm involving the cervix. "Up-regulation of SFN expression promoted the proliferation, cytoskeletal remodeling, migration and invasion of cervical cancer cells, and enhanced the expression of p-LIMK2, LIMK2, Cofilin and p-Cofilin." (PMID 37946061, 2024). "SFN can regulate cervical cancer cell proliferation, cytoskeletal remodeling and metastasis through LIMK2/Cofilin signaling." (PMID 37946061, 2024). "SFN knockdown significantly reduced the migration and invasion of cervical cancer cells, down-regulated the expression of p-LIMK2, LIMK2, Cofilin and p-Cofilin, inhibited cytoskeletal remodeling, and increased the apoptosis index of cervical cancer cells." (PMID 37946061, 2024). "SFN can regulate cervical cancer cell proliferation, apoptosis, cytoskeletal remodeling and metastasis through LIMK2/Cofilin signaling." (PMID 37946061, 2024). "LIMK2 inhibitor, at therapeutic doses, can represent a therapeutic agent to be further investigated to treat cervical cancer." (PMID 37946061, 2024). "Our results complement the current mechanism of action by which SFN regulates the development and progression of cervical cancer cells through the LIMK2/Cofilin signaling pathway, providing a potential target for cervical cancer treatment." (PMID 37946061, 2024). "Furthermore, our study provides compelling evidence for the pivotal role of LIMK2 in cervical cancer cell metastasis, as demonstrated by the utilization of a potent LIMK2 inhibitor." (PMID 37946061, 2024). "This study aims to investigate whether SFN regulates the metastasis of cervical cancer cells through the LIMK2/Cofilin signaling pathway." (PMID 37946061, 2024). "Based on these observations, it is reasonable to think that SFN may regulate cervical cytoskeletal remodeling through LIMK2/Cofilin pathway and affect the metastasis of cervical cancer cells." (PMID 37946061, 2024). "Notably, the SFN and LIMK2/Cofilin signaling pathways converge to actively participate in the remodeling of the cellular cytoskeleton, thus suggesting a plausible mechanism by which SFN orchestrates cervical cancer cell metastasis via modulation of the LIMK2/Cofilin signaling pathway." (PMID 37946061, 2024).
fibrosarcoma (1 paper, 2010). A malignant mesenchymal fibroblastic neoplasm affecting the soft tissue and bone. "In fibrosarcoma, the reduced expression in LIMK2 protein was found to restrict the metastatic potential." (PMID 21637621, 2010).
gastric cancer (1 paper, 2025). A primary or metastatic malignant neoplasm involving the stomach. "The distinct overexpression of LIMK1 in gastric cancer makes it a more attractive therapeutic target compared to LIMK2." (PMID 40367093, 2025). "In contrast, the expression level of LIMK2 in gastric cancer is relatively lower, and its specific role has not been fully elucidated." (PMID 40367093, 2025).
infertile (1 paper, 2023). "Similar results are observed for mice with a disrupted LIMK2 gene in which the progression of spermatogenesis is strongly affected and for humans where mutations in the heterozygous state in LIMK2 are present in infertile males." (PMID 37510406, 2023).
lung carcinoma (1 paper, 2014). "A549 cells were selected as a LIMK2 non-related cancer cell type, but based on the Lung cancer prevalence Worldwide." (PMID 25593987, 2014).
ocular hypertension (1 paper, 2021). Abnormally high intraocular pressure. "A dual inhibitor of LIMK2 and ROCK (LIMK2, IC50 7.5 nM), LX7101, has completed a Phase 1/2a study in primary open-angle glaucoma and ocular hypertension (NCT01528111) but the results are yet to be made available." (PMID 34100887, 2021).
ovarian carcinoma (1 paper, 2018). A malignant neoplasm originating from the surface ovarian epithelium. "EPHB4, in turn, is linked with the proliferation of ovarian carcinoma cells and LIMK2 with actin microfilament disruption in porcine oocytes." (PMID 30338064, 2018).
RASopathy (1 paper, 2024). Developmental syndromes caused by germline mutations (or in rare cases by somatic mosaicism) in genes that alter the Ras subfamily and mitogen-activated protein kinases that control signal transduction. "RASopathy patients exhibit alterations in the expression and activation of proteins in several signaling pathways, including RAS/MAPK, PI3K/AKT/mTOR, Rho/ROCK/LIMK2/cofilin, cAMP/PKA, JAK/STAT, Hippo, Wnt/β-catenin, and TGF-β." (PMID 39201250, 2024). "mRNAs, non-coding RNAs, protein expression patterns, and post-translational modifications characteristic of RASopathy patients within pivotal signaling pathways such as the RAS/MAPK, PI3K/AKT/mTOR, and Rho/ROCK/LIMK2/cofilin pathways are summarized." (PMID 39201250, 2024).
thyroid (1 paper, 2012). "Among the selected genes in the 22q area, CHEK2, LIMK2, and TIMP3 have already been reported to be deleted/down-regulated in thyroid cancer; the 22q deletion may play a role in thyroid carcinogenesis." (PMID 22558328, 2012).
tumor (34 papers, 2013 to 2025). "Higher expression of LIMK2 and p‐cofilin has been associated with anti‐tumour effect through inhibition of stem cell proliferation and tumour cells invasiveness." (PMID 35043584, 2022). "In summary, we observed progressive downregulation of LIMK2 from normal colon mucosa to SA tissue to CRC tissue, and LIMK2 was especially associated with tumor progression, suggesting its relation to tumor progression." (PMID 29970879, 2018). "Abnormal expression of LIMK1 and LIMK2 is implicated in various malignancies, and is known to be important in tumor manifestation and malignancy." (PMID 25593987, 2014). "The GO analysis results revealed that genes comutated with LIMK2 were involved in the immune response; therefore, it is reasonable to suspect that LIMK2 may be associated with the tumor immune response." (PMID 35273591, 2022). "In numerous tumor studies, it has been established that LIMK2, through phosphorylation of cofilin, modulates actin polymerization, thereby restraining tumor cell invasion." (PMID 37946061, 2024). "The LIMK2 differential gene expression levels were significantly higher in normal tissues than in tumors, demonstrating that it is a possible tumor suppressor gene." (PMID 38137332, 2023). "Put together, LIMK2 is a novel prognostic biomarker and correlates with tumor immune cell infiltration in LUSC, and the expression of LIMK2 is regulated by the PVT1 and DHRS4-AS1/miR-423-5p axes." (PMID 35273591, 2022). "As NKX3.1 is a prostate-specific tumor suppressor, preserving its levels by LIMK2 inhibition provides a tremendous opportunity for developing targeted therapy in CRPC." (PMID 34066036, 2021). "The reduction in ANXA2 and LIMK2 expression inhibits the NF-κB and Wnt/β-catenin signaling pathways and thus promotes BC tumor progression." (PMID 33526057, 2021). "For example, in bladder cancer (BC), NUDT21 regulates the expression of ANXA2 and LIMK2 in the Wnt/β-catenin and NF-κB signaling pathways and inhibits tumor progression." (PMID 33526057, 2021). "Among 22 genes with a negative regression coefficient, loss of IGFBP7 expression showed a role in thyroid carcinogenesis, LIMK2 showed a potential role as a tumor suppressor, consistent with this study." (PMID 30729678, 2019). "We characterized NUDT21-regulated genes with shortened 3′-UTRs, and found that ANXA2 and LIMK2 contribute to NUDT21-mediated tumor suppression by augmenting Wnt and NF-κB signaling." (PMID 31695759, 2019). "LIMK1, which shares a strong homology with LIMK2, promotes tumor proliferation and metastasis in various tumors, including CRC." (PMID 29970879, 2018). "Reduced LIMK2 expression enhanced the nuclear accumulation of β-catenin and activated the Wnt signaling pathway, thus contributing to tumor progression." (PMID 29970879, 2018). "A homolog of the LIMK family, LIMK1, which was overexpressed throughout tumor progression, served as a competitive inhibitor of LIMK2 via β-catenin nuclear translocation." (PMID 29970879, 2018). "Compared with the control group, more and larger tumor nodules were found in the livers of mice in the LIMK2-silenced group." (PMID 29970879, 2018). "Recent reports illustrate that LIMK2 is involved in tumor growth, and induces migration and invasion of tumor cells." (PMID 28069000, 2017). "The expression of p-cofilin and LIMK2 are both inhibited by tumor metastasis and restored by RLH activation." (PMID 27198666, 2016). "LIMK2 expression is associated with CRC progression, and its deletion affects gastrointestinal stem cell regulation and tumor development." (PMID 26207919, 2015). "The dysregulation of the regulation of actin cytoskeleton pathway plays a key role in the progression of CRC; this pathway contains a differential gene LIMK2 that promotes tumor-cell invasion and metastasis." (PMID 26207919, 2015). "LIMK2 is now thought to be an important player in tumor cell invasion and metastasis, especially in pancreatic, breast, and neuronal cancers." (PMID 25593987, 2014).
tumor (continued). "Towards this end, we queried if LIMK1 and LIMK2 had prognostic value in a clinically annotated dataset (REpository of Molecular BRAin Neoplasia DaTa/REMBRANDT)." (PMID 25237832, 2014). "To date, inhibitors targeting LIMK1 and LIMK2 have shown potent tumor-suppressive effects." (PMID 37894409, 2023). "Our model suggests that LIMK2 acts as a tumor suppressor gene." (PMID 37189142, 2023). "Moreover, the tumours derived from LIMK1/LIMK2-knockdowned TICs were significantly smaller, as they grew slower compared to the tumours derived from the control TICs." (PMID 36899941, 2023). "Our study indicated that LIMK2 might function as a tumor suppressor by decreasing tumor immune infiltration and restricting the expression of immune checkpoints." (PMID 35273591, 2022). "The results above demonstrated that LIMK2 could improve the survival of LUSC patients by suppressing the immune response of the tumor microenvironment, which further showed that LIMK2 could be used as a prognostic marker in patients with LUSC." (PMID 35273591, 2022). "First, a subcutaneous tumor model was established to evaluate the tumorigenesis of LIMK2." (PMID 29970879, 2018). "Since LIMK2 is known to play a prominent role in cancer, we wanted to find out whether T56-LIMKi inhibits tumor growth and tumor cell death." (PMID 25593987, 2014). "Furthermore, suppression of LIMK2 in human fibrosarcoma cells or expression of a dominant negative LIMK1 in an animal model of tumor invasion, limited cell migration and efficiency to form dense colonies without affecting cell proliferation rate or viability." (PMID 24093776, 2013). "LIMK2 might serve as a tumor marker to indicate the level of tumor progression." (PMID 29970879, 2018). "ROBO1, KLK6, LIMK2, KLK7, NLGN4X, MBP, and NEDD9 expression levels were significantly higher in normal tissues than in tumors, demonstrating the possibility of being a tumor suppressor gene." (PMID 38137332, 2023). "Next, we evaluated the expression of LIMK2 and PI4K2B in SCLC tumor and normal tissues by using GSE40275 and GSE60052 datasets." (PMID 37189142, 2023). "Studies have shown that LIMK2 expression is downregulated in CRC patients and continues to be downregulated as the tumor deteriorates." (PMID 37894409, 2023). "This study focuses on the tumor-suppressor NKX3.1, which was uncovered as a direct substrate of LIMK2 using an inventive screen." (PMID 34066036, 2021). "LIMK2 was reduced in SA and CRC tissues to various degrees, and LIMK2 expression was progressively downregulated with the advancement of tumor development." (PMID 29970879, 2018). "Extensive search of the literature revealed a potential key role of genes at the identified porcine loci in tumor invasion (DST, PLEKHA5, CBY1, LIMK2 and ETV5) and immune response modulation (ETV5, HERC3 and DICER1) of the progression phenotypes." (PMID 29963229, 2018). "Our research detected the expression of LIMK2 in normal, SA and CRC tissues and verified that LIMK2 was progressively downregulated with tumor development." (PMID 29970879, 2018). "The differential gene expression levels between the tumor and adjacent tissue indicated that the ROBO1, KLK6, LIMK2, KLK7, NLGN4X, MBP, and NEDD9 gene expression levels were higher in normal tissues than in tumors; however, EFNA1 was higher in the tumor than the normal ones." (PMID 38137332, 2023). "In BC tumor tissues, downregulation of NUDT21 promotes the production of ANXA2 and LIMK2 transcripts with longer 3’UTRs, thereby reducing the expression of ANXA2 and LIMK2." (PMID 33526057, 2021). "We further observed an overall negative association between NME4 and tumor invasion markers like genes encoding matrix-degrading proteases (MMP7, ADAM17) and actin cytoskeleton remodelers (ROCK1, ROCK2, LIMK2, CFL2, MYO5A)." (PMID 34674701, 2021). "The finding that LIMK2 influences metastatic attributes but not tumor growth is intriguing, but not unprecedented." (PMID 32859889, 2020).